PM20D1 (peptidase M20 domain containing 1)
Description:
Secreted enzyme that regulates the endogenous N-fatty acyl amino acid (NAAs) tissue and circulating levels by functioning as a bidirectional NAA synthase/hydrolase. It condenses free fatty acids and free amino acids to generate NAAs and bidirectionally catalyzes the reverse hydrolysis reaction. Some of these NAAs stimulate oxidative metabolism via mitochondrial uncoupling, increasing energy expenditure in a UPC1-independent manner. Thereby, this secreted protein may indirectly regulate whole body energy expenditure. PM20D1 circulates in tight association with both low- and high-density (LDL and HDL,respectively) lipoprotein particles (By similarity).
Synonyms: FLJ32569; Cps1
Tractability: Antibody: its Gene Ontology location is reachable by antibodies, with high confidence; UniProt places it where antibodies can reach, with medium confidence; UniProt predicts a signal peptide or a membrane-spanning region.
Gene: Protein-coding gene on chromosome 1 (205,828,025 to 205,850,132, reverse strand). Ensembl gene ENSG00000162877.
Subcellular location: Secreted
Pathways (Reactome):
Metabolism: Oleoyl-phe metabolism
Gene Ontology:
Molecular function: hydrolase activity, acting on carbon-nitrogen (but not peptide) bonds, in linear amides; aminoacylase activity; hydrolase activity
Biological process: amino acid metabolic process; lipid metabolic process; adaptive thermogenesis; energy homeostasis; fatty acid metabolic process
Cellular component: extracellular exosome; extracellular region
Genetic constraint (gnomAD): Loss-of-function variants: 47 observed, 50.94 expected, observed/expected ratio (o/e) 0.92, 90% interval 0.73 to 1.18. The upper end of that interval is the gene's LOEUF score, 1.18, which puts it in group 5 of 6, group 1 being the genes least tolerant of losing a copy. Missense variants: 539 observed, 593.9 expected, observed/expected ratio (o/e) 0.91, 90% interval 0.85 to 0.98. Synonymous variants: 232 observed, 236.98 expected, observed/expected ratio (o/e) 0.98, 90% interval 0.88 to 1.09.
Homologues: Orthologues: chimpanzee PM20D1 (99% identical), macaque PM20D1 (83% identical), guinea pig PM20D1 (76% identical), dog PM20D1 (75% identical), rat Pm20d1 (72% identical), mouse Pm20d1 (72% identical), rabbit PM20D1 (71% identical), pig PM20D1 (69% identical), tropical clawed frog pm20d1 (57% identical), zebrafish pm20d1.2 (49% identical), zebrafish pm20d1.1 (48% identical). Paralogues in human: CNDP2 (18% identical), CNDP1 (17% identical), ACY1 (15% identical).
Diseases named in the same sentence as PM20D1 in open-access papers:
PM20D1 is named in the same sentence as 44 diseases in open-access papers, as found by Europe PMC text mining. Sharing a sentence is not in itself a finding about the gene and the disease. The quoted sentences say what the papers report.
Obesity (10 papers, 2016 to 2025). Accumulation of substantial excess body fat. "PM20D1 has also been associated with diabetes, obesity, and multiple sclerosis, and since it is localized within the PARK16 locus, its possible involvement/association with PD is assumed." (PMID 35163527, 2022). "PM20D1, encoding a secretory enzyme-producing bioactive N-acyl amino acids and associated with obesity and neurodegenerative diseases, was the most highly differentiated gene between the Mongolians and CEAs." (PMID 35986394, 2022). "PM20D1 codes for Peptidase M20 Domain Containing 1 and was found to be hypermethylated in association with obesity, stroke, childhood abuse and now RA (current study)." (PMID 26999364, 2016). "Polymorphisms within and near the human PM20D1 gene are linked to body mass index, providing powerful genetic evidence that PM20D1 may also regulate human obesity and metabolic disorders." (PMID 32271712, 2020). "In addition, PM20D1 itself has also been related to several disorders characterized by high levels of ROS, such as diabetes and obesity, and to neurodegenerative diseases with strong mitochondrial alterations, including multiple sclerosis and PD." (PMID 32014019, 2020). "And some other biomarkers closely related to obesity and metabolic syndrome components, such as adiponectin, fetuin-A and Peptidase M20 domain containing 1 (PM20D1) measurement of their serum concentrations may be valuable for clinical diagnosis of IR-related metabolic and cardiovascular diseases." (PMID 37056675, 2023). "Peptidase M20 domain containing 1 (PM20D1) and Slit2 are two newly identified batokines that improves glucose homeostasis as well as regulate thermogenesis which might be used for the treatment of obesity and obesity associated metabolic disorders." (PMID 33511131, 2020). "Interventions that promote bidirectional changes in BAT Pm20d1 shift the metabolic phenotypes; so, BALB/c under partial inhibition of Pm20d1 becomes obesity prone and cold-intolerant, whereas C57BL/6 under increased expression of Pm20d1 presents reduced body mass gain and becomes cold-tolerant." (PMID 40877813, 2025).
Alzheimer disease (7 papers, 2019 to 2026). A progressive, neurodegenerative disease characterized by loss of function and death of nerve cells in several areas of the brain leading to loss of cognitive function such as memory and language. "mQTL-dependent PM20D1 hypermethylation is also associated with Alzheimer’s disease." (PMID 35986394, 2022). "Seven of the heritable methylation marks associated with prostate cancer risk are located at peptidase M20 domain containing 1 (PM20D1), a known methylation and expression quantitative trait locus associated with risk of Alzheimer’s disease." (PMID 36708485, 2023). "Further, the PM20D1 promoter methylation levels showed a modest positive correlation with age in PBCs from Alzheimer’s disease patients." (PMID 35986394, 2022). "Recent reports highlight several examples, including SPATC1L in male infertility, PM20D1 in Alzheimer’s disease, and DUSP22 in lymphoma." (PMID 31155008, 2019). "Furthermore, the PM20D1 (Peptidase M20 domain containing 1) promoter is highly methylated in the postmortem prefrontal neurons of Alzheimer’s disease patients." (PMID 35986394, 2022). "Similarly, PM20D1, involved in the amide biosynthesis and regulation of neuron death, has been related to enhanced glucose homeostasis in mice and also DNA methylation changes in PM20D1 linked to PTSD and Alzheimer’s disease." (PMID 38516266, 2024). "Interestingly, novel findings of Sachez-Mut and colleagues indicate that PM20D1 (peptidase M20 domain containing 1) methylation and expression are dependent on the SNP rs708727, and that both the epigenetic regulation of PM20D1 and the genetic variation at rs708727 are linked to Alzheimer’s disease." (PMID 31546642, 2019).
Parkinson disease (5 papers, 2018 to 2025). A progressive degenerative disorder of the central nervous system characterized by loss of dopamine producing neurons in the substantia nigra and the presence of Lewy bodies in the substantia nigra and locus coeruleus. "PM20D1, encoding an N-fatty acyl amino acid (NAAs) synthase/hydrolase, is located within a Parkinson’s susceptibility locus." (PMID 36575526, 2022). "Among them, the MCCC1 gene is involved in mitochondrial homeostasis and was shown to be associated with sporadic Parkinson’s disease in multiple GWAS; PM20D1 is associated with response to accumulation of amyloid-β in AD brains." (PMID 36109771, 2022). "Supporting this, we found a clear example of a cell-type-independent mQTL mapping to the 1q32 locus of the PM20D1 gene, a major genome-wide association study (GWAS) locus associated with Parkinson’s disease." (PMID 29884221, 2018).
COVID-19 (3 papers, 2022 to 2023). A disease caused by infection with severe acute respiratory syndrome coronavirus 2. "We found no missense variants with a potential causal function on resistance to COVID-19; however, two missense variants were determined as significant a severe phenotype (in PM20D1 and LRP4 exons)." (PMID 36662838, 2023). "None of identified significant SNPs (in the intron of AJAP1 and the intron of FIG4) and none of the missense variants with a potential causal function on a severe outcome of COVID-19 (in the exon of PM20D1 and the exon of LRP4), found in our study, have been previously associated with COVID-19." (PMID 36662838, 2023). "In particular, we showed that DNA methylation at several CpGs, e.g., cg14893161 (annotated to PM20D1), may play an important role in relation to COVID-19 severity." (PMID 36380121, 2022). "Our analysis highlighted three COVID-related CpGs annotated to genes PM20D1 and UBAP2L that were putatively causal for COVID-19 severity; more research is needed to understand if and how these CpGs might influence outcome in patients with the COVID-19." (PMID 36380121, 2022). "Our observation that two of the targeted methylated genes within EPIMISC were shared with severe adult COVID-19 cases (AIM2 and PM20D1) prompted us to investigate whether the EPIMISC signature was also present in non-pediatric COVID-19 cases." (PMID 35770252, 2022).
Insulin resistance (3 papers, 2020 to 2025). Increased resistance towards insulin, that is, diminished effectiveness of insulin in reducing blood glucose levels. "PM20D1, Peptidase M20 domain-containing 1, previously identified as a factor secreted by thermogenic adipose cells, is known for its association with insulin resistance, glucose intolerance and enhanced defense of body temperature in cold when knocked out in mice." (PMID 33045005, 2020). "These genes have been involved in insulin resistance and secretion (ATM, PTPRN2, PSMD10, and NSF), adipogenesis (SLC25A24 and PAX8), inflammatory processes (TNFRSF8 and SLIT3), and mitochondrial processes (PM20D1 and LCLAT1)." (PMID 36535927, 2022).
amyloid (2 papers, 2020 to 2022). "Sanchez-Mut and coworkers have demonstrated that the overexpression of PM20D1 in the murine AD hippocampus results in learning improvement, whereas its knock-down increases the amyloid plaque load." (PMID 35163527, 2022). "Forced overexpression of PM20D1 in the hippocampus results in improved learning performance in the mouse model of AD, whereas PM20D1 knockdown increases amyloid plaque load, so it has been suggested to have a protective role against AD." (PMID 33298155, 2020).
metabolic syndrome (2 papers, 2023 to 2025). A cluster of metabolic risk factors for CARDIOVASCULAR DISEASES and TYPE 2 DIABETES MELLITUS. "In humans, variants of the PM20D1 gene are associated with changes in body mass index, whereas at least one variant in the promoter region is associated with increased body mass index and metabolic syndrome." (PMID 40877813, 2025).
asthma (1 paper, 2016). "Also, according to GEOprofile dataset GSE5112, PM20D1 gene expression is regulated by the TLR5 pathway, which is critically involved in allergic responses and severe asthma." (PMID 26999364, 2016).
atherosclerosis (1 paper, 2024). A disease characterized by the build-up of fatty material and calcium deposition in the arterial wall resulting in partial or complete occlusion of the arterial lumen. "Furthermore, decreased expression of PM20D1 has been observed in cardiovascular diseases such as atherosclerosis and gestational diabetes, and lower PM20D1 levels are associated with increased secretion of inflammatory factors, impaired lipid metabolism, and worse prognosis in patients." (PMID 38614995, 2024).
cognitive decline (1 paper, 2021). "A similar DMR annotated to PM20D1 (chr1: 205,818,956 to 205,819,609 [12 probes], Sidak-corrected P = 7.00 × 10−5) was also associated with the rate of cognitive decline as measured by the slope of CDR-SB in patients with MCI." (PMID 34654479, 2021).
cystic fibrosis-related diabetes (1 paper, 2023). Cystic fibrosis-related diabetes is a form of diabetes that occurs frequently in individuals with cystic fibrosis. "Additional genes implicated in the development of cystic fibrosis-related diabetes (CFRD) include PM20d1, which is located near the SLC26A9 gene, and PTMA." (PMID 37893045, 2023).
dementia (1 paper, 2022). Loss of intellectual abilities interfering with an individual's social and occupational functions. "Taking these observations into consideration we speculate, whether the rs708727-linked activity that silences PM20D1 contributes to the PD-dementia onset, and whether the monitoring of PM20D1 activity can serve as a prognostic parameter for the onset of PD-dementia." (PMID 35163527, 2022).
idiopathic pulmonary arterial hypertension (1 paper, 2024). A sporadic form of pulmonary arterial hypertension (PAH) characterized by elevated pulmonary arterial resistance leading to right heart failure. "This study aimed to investigate the serum levels of Peptidase M20 domain containing 1 (PM20D1) in idiopathic pulmonary arterial hypertension (IPAH) patients and examine its association with lipid metabolism, echocardiography, and hemodynamic parameters." (PMID 38614995, 2024).
polycystic ovary syndrome (1 paper, 2024). A disorder that manifests as multiple cysts on the ovaries. "DEGs for the Dormant (O1) subcluster encompass Ankrd36, whose mutation has been implicated in diminished ovarian reserve, as well as Pm20d1, which has been noted for its potential involvement in the pathogenesis of polycystic ovary syndrome." (PMID 39441825, 2024).
neurodegenerative disease (5 papers, 2020 to 2025). A disorder of the central nervous system characterized by gradual and progressive loss of neural tissue and neurologic function. "We therefore suggest that the decreased PM20D1 expression, the subsequently lower abundance of NADA, and the increased activity of 5-LOX significantly contribute to the pathology of PD (and other neurodegenerative diseases)." (PMID 35163527, 2022).
cancer (2 papers, 2019 to 2025). A tumor composed of atypical neoplastic, often pleomorphic cells that invade other tissues. "PM20D1 is related to the metabolism pathway, and it may be involved in cancer via influencing tumor metabolism (data no shown)." (PMID 31706267, 2019).
neurological diseases (1 paper, 2020). "The activation of the PM20D1/N-acyl amino acid pathway is suggested as a contributor to the protection from metabolic and neurological diseases observed in APOE-KO mice." (PMID 33298155, 2020).
PM20D1 also shares sentences with these, for which no sentence is quoted: metabolic disorders (4 papers); cardiovascular diseases (2); diabetes (2); multiple sclerosis (2); prostate carcinoma (2); tumor (2); Allergy (1); autism (1); autism spectrum disorder (1); bladder cancer (1); cardiomyopathy (1); depression (1); gastric cancer (1); gestational diabetes (1); Glucose intolerance (1); infection (1); lymphoma (1); male infertility (1); pancreatic cancer (1); Parkinson (1); post-traumatic stress disorder (1); psoriasis (1); psychiatric disorder (1); schizophrenia (1); Sepsis (1); skin cancer (1); Stroke (1).